COL1A1 (collagen type I alpha 1 chain)
Diseases named in the same sentence as COL1A1 in open-access papers (continued):
Sharing a sentence is not in itself a finding about the gene and the disease.
asthma (14 papers, 2017 to 2024). "Additionally, an in vitro asthma study indicated that cyclopamine and GANT61 alleviated the TGFβ1-induced increase in COL1A1 expression, implying that the activation of Hh signaling in asthma is caused, at least in part, by TGF-β, resulting in the airway remodeling." (PMID 39766192, 2024). "BSMCs treated with polyI:C alone displayed an increase in the mRNA expression of FN1 and COL1A1 compared to untreated cells, and this effect was observed to a higher extent in asthma and COPD as compared to control groups (p < 0.05)." (PMID 34512638, 2021). "Among all the MYH11 + COL1A1 + stromal cells, we observed a significant increase in the cell proportion of Myo/SMC and VSMC in AS compared to NC (Fisher’s exact test, FDR < 0.05), suggesting an abnormal increase of myofibroblast and VSMC associated with the pathology of asthma." (PMID 38317239, 2024). "In this study, asthma patients’ eosinophil subtypes, especially SEA patients’ rEOS-like cells, upregulated COL1A1, and FN gene expression in ASM cells, which could cause increased production of ECM proteins collagen I and fibronectin and subsequently promote ASM cell migration." (PMID 36834879, 2023). "The findings of positive association between the gene expression of various collagens (i.e., COL5A1 and less significantly COL1A1) and ATG5 supported the speculation that enhanced autophagy is associated with asthma pathogenesis and in particular collagen deposition." (PMID 28424691, 2017). "Increased anti-fibrotic effect of 1,25D3 was observed in BSMCs from asthma (FN1 average fold-decrease 6.78 ± 0.65, p < 0.001; COL1A1 average fold-decrease 3.68 ± 1.21, p < 0.05 p = 0.014) compared to BSMCs from COPD." (PMID 34512638, 2021). "Our findings indicated that pro-inflammatory and pro-fibrotic mediators are increased at the baseline in BSMCs from both asthma and COPD, and that TLR3 agonist polyI:C, significantly upregulated IL-6, IFN-β1, CCL2, FN1 and COL1A1 expressions in BSMCs." (PMID 34512638, 2021). "We aimed to evaluate the effect of in vivo allergen-activated eosinophils on the expression of COL1A1 and FN in ASM cells in asthma." (PMID 32155894, 2020). "The combined interaction scores resulted in higher interactions for the genes STAT3, AGO2, COL1A1, CLCN6, and KSR for moderate asthma and JAK2, INSR, ERBB2, NR3C1, and PTK6 for severe asthma." (PMID 32512817, 2020). "COL1A1 expression was positively associated with the amount of collagen in the airway in asthmatics and non-asthmatics (Collagen/Pi, R2 = 0.2221 and 0.2182 for asthma and non-asthma respectively, p < 0.01) and the thickness of the basement membrane in both groups combined (R2 = 0.1313, p = 0.01)." (PMID 29228930, 2017). "Thus, we decided to investigate eosinophil subtypes’ effect on ASM cell migration, ECM-related proliferation, and main ECM-related COL1A1, FN, TGF-β1, and contractile apparatus protein gene expression in asthma." (PMID 36834879, 2023). "In conclusion, our study revealed that BT was effective in 81% of patients irrespective of asthma endotypes and was associated with a reduction in ACTA2 and an increase in FAP, COL1A1, COL1A2 and CD68 gene expression." (PMID 35534846, 2022). "For example, in severe asthma, the combined interaction scores for the STAT3, AGO2, COL1A1, CLCN6, and KSR1 genes yielded a higher interaction for the moderate asthma phenotype, and the JAK2, INSR, ERBB2, NR3C1, and PTK6 genes were more interactive for the severe asthma phenotype." (PMID 32512817, 2020). "These genes may explain certain features of asthma severity, including allergic response (STAT3) and inflammation in asthmatic airways (NR3C1 and COL1A1)." (PMID 32512817, 2020). "Myofibroblasts contribute to airway remodeling in the long-term complication of asthma depending on the inflammatory microenvironment; one of the principal products of these pathological cells are αSMA fibers; TGF-β1 induces transient upregulation of COL1A1 and αSMA important fibrosis markers." (PMID 39000141, 2024).
asthma (continued). "Expression of α-SMA and COL1A1 by HLFs cultured with BECs from children with asthma and a history of severe exacerbations was not significantly different than expression by HLFs cultured with BECs from asthmatic children without a history of severe exacerbations." (PMID 30361541, 2018).
cervical carcinoma (14 papers, 2017 to 2026). A carcinoma arising from either the exocervical squamous epithelium or the endocervical glandular epithelium. "The results showed that high COL1A1 expression was associated with the proliferation and metastasis of cervical cancer." (PMID 38979664, 2024). "FBXL19‐AS1 promotes the proliferation and metastasis of cervical cancer cells by sponging miR‐193a‐5p and up‐regulating COL1A1." (PMID 38979664, 2024). "lncRNA FBXL19-AS1 enhances metastasis and proliferation by miR-193a-5p/COL1A1 axis in cervical cancer." (PMID 35847361, 2022). "Meanwhile, we determined the COL1A1 protein levels in 70 cervical cancer tissues and 10 normal samples by high throughput IHC analyse." (PMID 28775672, 2017). "For COL1A1 IHC staining in cervical cancer, immunoreactivity was primarily observed in the ECM (extracellular matrix) of tumor cells." (PMID 28775672, 2017). "In the present study, we evaluated the possibility of COL1A1 as a therapeutic target of cervical cancer." (PMID 28775672, 2017). "Here, based on the study of clinicopathological tissues and cell models, we found that COL1A1 played an important role in inhibiting apoptosis induced by radiation in cervical cancer cells." (PMID 28775672, 2017). "This is the only study to profile that COL1A1 is a crucial radioresistance factor in cervical cancer cells and plays an important role in ant-apoptosis by Caspase-3/PI3K/AKT pathways." (PMID 28775672, 2017). "The expression of COL1A1 was significantly increased in cervical cancer tissues compared with normal tissues at the mRNA and protein level." (PMID 28775672, 2017). "The effect of COL1A1 on radioresistance of human cervical cancer cell lines HeLa and CaSki was assessed using the colony formation assay." (PMID 28775672, 2017). "Expression of COL1A1 in cervical cancer tissues and normal tissues was assessed by qRT-PCR and immunohistochemistry." (PMID 28775672, 2017). "The baseline expression of COL1A1 was explored in cervical cancer cell lines: Hela, CaSki and SiHa." (PMID 28775672, 2017). "Therefore, our results suggest that COL1A1 expression was enhanced from normal cervical specimens to different grades cervical cancers gradually." (PMID 28775672, 2017). "LY29400 and X-ray radiation were used to treat cervical cancer cells with COL1A1 activation." (PMID 28775672, 2017). "Regarding to the molecular mechanism which leading to the COL1A1 overexpression in cervical cancer, we are thinking that COL1A1 might be induced by activation of radiation dependent Caspase-3/PI3K/AKT signaling pathway." (PMID 28775672, 2017). "Furthermore, a close relationship was observed between the increasing grade of lesion and the intensity of COL1A1 staining in cervical cancer tissues." (PMID 28775672, 2017). "In addition, Kitahara’s cDNA microarray analysis result has indicated that COL1A1 is involved in radioresistance of cervical cancer." (PMID 28775672, 2017). "In the present study, we hypothesize that COL1A1 is crucial for radioresistance in cervical cancer cells with RT." (PMID 28775672, 2017). "A recent study found that COL1A1 activation could suppress the apoptosis of cervical cancer cells." (PMID 35646104, 2022). "Moreover, the findings are further supported by apoptosis analysis that COL1A1 activation could inhibit the apoptosis of cervical cancer cells." (PMID 28775672, 2017). "Therefore, we can get the conclusion that COL1A1 Activation may decrease apoptosis of cervical cancer cells by destroying the balance between anti-apoptotic and pro-apoptotic proteins and activating Caspase-3/PI3K/AKT pathway." (PMID 28775672, 2017). "The expression levels of Col1A1, Col3A1, Col4A1 and HIF-1α were positively correlated with P4HA2 levels in TCGA cervical cancer cohort (P < 0.001)." (PMID 32226497, 2020). "First evidence from our group demonstrated, the expression of COL1A1 up regulation at mRNA and protein levels from grade I to III in cervical cancer tissues, in contrast to normal cervical tissues." (PMID 28775672, 2017).
cervical carcinoma (continued). "Although the important roles of COL1A1 in tumor progression in multiple cancers are now being clarified, it has not been studied in development of cervical cancer." (PMID 28775672, 2017). "Therefore, our identification of radioresistance-related COL1A1 in cervical cancer could be a starting point to explore the function of collagens, adding a new dimension to our understanding of the cervical cancer, assisting cancer biologists and clinical oncologists in novel therapeutic strategies." (PMID 28775672, 2017).
lung adenocarcinoma (13 papers, 2020 to 2025). A carcinoma that arises from the lung and is characterized by the presence of malignant glandular epithelial cells. "COL1A1 has been reported to be closely associated with the prognosis of patients with lung adenocarcinoma, lung squamous carcinoma and esophageal cancer." (PMID 37476379, 2023). "The CAF marker of COL1A1 indicated overall survival and disease-free survival more efficiently in early staged lung adenocarcinoma." (PMID 39034310, 2024). "In our previous research, we identified collagen type 1 alpha 1 chain (COL1A1) as the key gene during the development and progression of lung adenocarcinoma (LUAD) by multi-omics analysis." (PMID 34475986, 2021). "Our previous study identified that COL1A1 is the key gene during the development and progression of lung adenocarcinoma by multi-omics analysis." (PMID 34475986, 2021). "The expression of COL1A1, COL1A2, and COL3A1, members of the collagen family, is increased in lung adenocarcinomas and is associated with its poor prognosis." (PMID 34326696, 2021). "Higher proportions of CAF cells were correlated with shorter survival in lung adenocarcinoma (LUAD), particularly when using COL1A1 as a marker." (PMID 39034310, 2024). "Our investigation revealed that COL1A1, COL1A2, FAP, and PDGFRA are effective markers for characterizing CAF subgroups in most lung adenocarcinoma datasets." (PMID 39034310, 2024). "We detected a relationship between C1q and TGF-β1 as well as other mesenchymal markers (ACTA2, COL1A1, and CTGF) in lung adenocarcinoma using the online tool TIMER2.0." (PMID 35078421, 2022).
atherosclerosis (12 papers, 2018 to 2025). A disease characterized by the build-up of fatty material and calcium deposition in the arterial wall resulting in partial or complete occlusion of the arterial lumen. "To validate sensitivity towards the known genes implicated in phenotypic switching of SMCs in atherosclerosis, we confirmed that markers of synthetic SMCs (Fn1, Col1a1, Col3a1, Col1a2, Eln, and Vcam1) were elevated in SMCTRAP-AS compared with SMCTRAP." (PMID 38289873, 2024). "The common mechanisms shared in both are linked with atherosclerosis signaling and inflammatory response with at least the following target genes: Tnfrsf12a, Pla2g2f, Il1f9, Col1a1, Col1a2, and Col3a1 in brain, while Tnfrsf12a, SELP, SELE, IL6, and IL1A in myocardium." (PMID 29681850, 2018). "In fact, COL1A1 is key to many diseases, such as atherosclerosis, myocardial fibrosis, heart failure, and osteogenesis imperfecta." (PMID 38195542, 2024). "On the other hand, atherosclerosis related hsa-miR-143-3p targets in VSMCs included CACNA1C, COL1A1, and PTGS2, which are associated with VSMC contraction, extracellular matrix synthesis, and proliferation." (PMID 32397522, 2020). "An unannotated disease-specific cell cluster (A-cluster 6) co-expressed contractile VSMC markers (Myh11, Acta2, and Cnn1) with several atherosclerosis-induced ECM genes (Col1a1, Mgp, Eln, Fn1, Col4a1, and Col8a1) and had reduced levels of Ly6a, Vcam1, and Tnfrsf11b compared to imVSMCs." (PMID 40577585, 2025). "Additionally, a cell population co-expressing contractile genes with key ECM genes (Col1a1, Mgp, Eln, Fn1, Col4a1, and Col8a1) and Notch3, mapped together with the fcVSMC population from the atherosclerosis dataset (I-cluster 6)." (PMID 40577585, 2025). "Unsupervised DEGs analysis of SMCs revealed increased expression in Abcb8ECKO of TGF-β-pathway genes such as Tgfb1, Tgfb2, Tgfb3, Mmp2 and Col1a1, inflammatory genes such as Ccl2 (encoding for MCP1) and Csf1 as well as atherosclerosis-associated genes including Egr1, Sqstm1, Irf1, Sox4 and Xylt1." (PMID 41252867, 2025). "For example, mice expressing collagen with an introduced mutation that abrogates the classic collagen I cleavage site (Col1a1 (r/r) mice) provided vital information about the role of collagen turnover in bone, wound healing, atherosclerosis and post-partum uterine remodeling." (PMID 34195596, 2021). "Ten key regulated genes (including Pla2g2f, Il1f9, Col1a1, Col1a2, and Col3a1 in the brain, while SELP, SELE, IL6, and IL1A in the myocardium, and Tnfrsf12a in both) are correlative with atherosclerosis signaling and inflammatory response." (PMID 29681850, 2018). "This review focuses on the role and mechanism of action of miR-26 in atherosclerosis, including the detection value of miR-26 and the potential development of drugs targeting its downstream genes, such as ACC1/2, COL1A1, CPT1A, FBP1, DGAT2, and SMAD7, to provide insight for drug development." (PMID 38195542, 2024).
colitis (12 papers, 2019 to 2026). Inflammation of the colon. "Reduced expression of Col1a1 was detected after colitis induction, which is associated with reduced fibrosis." (PMID 38510236, 2024). "Since excessive collagen deposition may lead to the development of intestinal fibrosis, FRB seemingly reduced the risk of fibrosis due to DSS-induced colitis, by reducing the mRNA expression of Col1a1 and Col1a2 and increasing the level of Mmp3." (PMID 34070845, 2021). "Moreover, a slight decrease of colon mRNA expression of extracellular matrix-associated genes Fn1, Col1a1, Col3a1 and Tgf-β was observed in colitis mice receiving SuperMApo treatment." (PMID 35003066, 2021). "Supporting this is the observation that in a dextran sodium sulphate-induced colitis mouse model, decreased Col1a1 mRNA, decreased collagen protein deposition and decreased hydroxyproline content were noted following Ogr1 knock-out in comparison to the Ogr1 wild-type controls." (PMID 37373151, 2023). "Also, Col1a1 and Col3a1 were overexpressed during active inflammation and murine colitis induced by 2,4,6-trinitrobenzene sulfonic acid (TNBS) hapten." (PMID 32478052, 2020). "In murine DSS-colitis, BMP9 attenuated disease severity, colon shortening, histopathological damage, inflammatory cytokines, and early pro-fibrotic markers (Col1a1, Col3a1, α-SMA)." (PMID 41751187, 2026).
esophageal cancer (12 papers, 2021 to 2025). A primary or metastatic malignant neoplasm involving the esophagus. "The lncRNA BBOX1-AS1 was highly expressed in esophageal cancer, and the knockdown of miR-361-3p promoted COL1A1 expression, promoting esophageal cancer progression." (PMID 40191723, 2025). "We furthermore observed exclusive upregulation of several collagens (COL1A1, -9A1, -12A1, -27A1) in esophageal cancers with high CLDN6 levels." (PMID 37592303, 2023). "In esophageal cancer, Circ_0004370 up-regulates COL1A1 through sponging miR-1301 to promote the occurrence and development of esophageal cancer." (PMID 35070996, 2021). "KRT17 and COL1A1 are potential biomarkers for esophageal cancer in the Chinese population." (PMID 38979664, 2024). "Core genes KRT17 and COL1A1 were used to test the efficacy of esophageal cancer." (PMID 38979664, 2024).
Osteopenia (12 papers, 2012 to 2025). Osteopenia is a term to define bone density that is not normal but also not as low as osteoporosis. "In case 93926 with mild rhizomelia, osteopenia, several fractures and a coronal cleft, and metaphyseal chondrodysplasia, a de novo mutation was detected in COL1A1 (c.3505G > A) (p.G1169S)." (PMID 33772059, 2021). "In the case of analysis of the rs1800012 COL1A1 polymorphism in the dominant model, the odds ratio was 1.59 (95%CI: 1.00–2.53), which means that the presence of at least one T allele (TT or GT) increases the risk of osteopenia by 59% (p = 0.052)." (PMID 41009461, 2025). "The results of this study suggest that the rs1800012 COL1A1 polymorphism may be a risk factor for osteopenia in postmenopausal women, particularly in interaction with environmental factors such as BMI and smoking." (PMID 41009461, 2025). "OASIS knockout mice displayed abnormally expanded rough ER and severe osteopenia due to reduced COL1A1 in the bone matrix and decreased activity of osteoblasts by targeting and activating COL1A1." (PMID 41184233, 2025). "In mice, overexpression of Sox9 in osteoblasts from a 2.3-kb Col1a1 promoter resulted in dwarfism and osteopenia, with a significant reduction in bone volume, osteoblasts number and bone formation rate." (PMID 29176883, 2017). "Sp7 transgenic mice under the control of 2.3 kb Col1a1 promoter showed osteopenia and woven-bone like structure in the cortical bone, which was thin and less mineralized, in a dose-dependent manner." (PMID 22396760, 2012). "Further, the osteopenia in Sp7 or Runx2 transgenic mice was worsened in Sp7/Runx2 double transgenic mice and the expression of Col1a1 and Bglap2 was reduced." (PMID 22396760, 2012). "Here, we show that deleting Kindlin-2 from osteoblasts using the 2.3-kb mouse Col1a1-Cre transgene minimally impacts bone mass in mice, but deleting Kindlin-2 using the 10-kb mouse Dmp1-Cre transgene, which targets osteocytes and mature osteoblasts, results in striking osteopenia in mice." (PMID 31934494, 2020).